MYD88 (MYD88 innate immune signal transduction adaptor)
Diseases named in the same sentence as MYD88 in open-access papers (continued):
Sharing a sentence is not in itself a finding about the gene and the disease.
infection (continued). "Gastric intrinsic factor was downregulated in H. felis-infected Myd88−/− mice at both 25 and 47 weeks post-infection." (PMID 28201999, 2017). "Here, we have shown that T cell-intrinsic IL-18R/MyD88 signaling is crucial for the development of a robust Th1 response induced by infection with the intracellular pathogen, T. cruzi." (PMID 28895840, 2017). "We show here that MyD88-/- mice exhibited decreased inflammasome activation, attenuated liver injury, and were more resistant to lethal infection than WT mice, despite suppressed protective immunity and increased bacterial burden in the liver." (PMID 29049365, 2017). "We suggest the existence of a functional, self-regulating node in infection, which contains MyD88, miR-125a-3p, miR-125b-5p and NTAN1." (PMID 28445535, 2017). "CXCL1 (C-X-C motif ligand 1) has been shown to be upregulated by TLR/MyD88 activation and is important in corneal wound healing and infection Therefore, we examined the baseline expression of this chemokine in untreated mice deficient in MyD88 or IL-1R." (PMID 28796783, 2017). "Few studies to date have directly addressed the relevance of T cell-intrinsic MyD88 signaling pathways for the establishment of in vivo cognate Th1 responses in the context of infection." (PMID 28895840, 2017). "In general, anti-DenV2 sera derived from DenV2-infected BL/6, TLR2 KO, and MyD88 KO mice were unable to completely neutralize DenV2 or DenV4 infection." (PMID 29285314, 2017). "The adoptive transfer of purified WT CD4+ T cells protects Il18r1−/− and Myd88−/− mice against infection with T. cruzi." (PMID 28895840, 2017). "For this, CD4+ T cells were sorted from infected WT mice to high purity levels and were then transferred to both Il18r1−/− and Myd88−/− mice, 20 hr before infection." (PMID 28895840, 2017). "A decrease in the accumulation of neutrophils and macrophages to the site of infection has been observed in MyD88−/− mutant mice." (PMID 27821583, 2017). "In summary, this study characterizes for the first time changes in miRNA expression upon macrophage infection by L. pneumopila in the context of MyD88 deletion." (PMID 28445535, 2017). "Infection of Myd88−/− mice resulted in the differential expression of 1,989 genes at 25 weeks (1031 up and 958 downregulated)." (PMID 28201999, 2017). "Single SK3842 infection caused induction of TLRs 4 and 9 but a drastic reduction of the central TLR adaptor protein, MyD88." (PMID 28300841, 2017). "The key role of MyD88 for the induction of protective host responses upon infection with C. rodentium has been well established using MyD88-deficient mice, which, in contrast to wild type (WT) mice, succumb rapidly to infections with this pathogen." (PMID 28520792, 2017). "Myd88-/- mice demonstrate a 60% reduction in IL-1β at 8 hours post-infection in comparison to WT mice, confirming the essential role of MyD88 for IL-1β induction." (PMID 28704551, 2017). "The ability of GGT to generate glutamate is required by C. jejuni for persistent commensal colonization of the chick ceca and infection of the intestinal tracts and livers of myd88−/− mice." (PMID 28487428, 2017). "On the other hand, there was a large impairment in the ability of Myd88-/- mice to recruit neutrophils to the skin, as they demonstrated an approximately 70% reduction in myeloperoxidase levels 8 hours after infection." (PMID 28704551, 2017). "The induction of miR-125a-3p, however, revealed a strong dependence on MyD88, as it was down-regulated in MyD88-/- cells upon infection, while robustly induced in WT cells." (PMID 28445535, 2017). "Muc5ac, which encodes gastric M1 mucin has been reported to play a role in gastric carcinogenesis was also downregulated in response to infection with H. felis in Myd88−/− mice." (PMID 28201999, 2017). "MyD88 mRNA transcripts were upregulated in tracheal samples from all challenged groups (A and B) and at all post-infection intervals." (PMID 28199419, 2017).
infection (continued). "The positive ADE regulation of DenV2 and DenV4 infectivity by TLR2/MyD88 pathway in primary anti-DenV2 sera was more evident when relative fold of infection enhancement to control was comparably displayed with the amount of total IgG protein." (PMID 29285314, 2017). "Firstly, we aimed to establish a solid set of markers to ensure efficient infection of BMMs with L. pneumophila and to show the perturbations inflicted by the MyD88 knockout." (PMID 28445535, 2017). "Since inflammasome activation is linked to severe liver injury in IOE-infected mice, we examined the contribution of MyD88 to inflammasome activation during IOE infection." (PMID 29049365, 2017). "After 96 hours of infection, 75 and 71.4% of MyD88 flies succumbed by C. glabrata ∆HTL and ∆HTL + Cas9 respectively." (PMID 27767081, 2016). "Other studies have found that the KSHV-encoded E3 ligase replication and transcription activator (RTA) was able to degrade MyD88 via ubiquitination and proteasomal degradation during early infection." (PMID 27070595, 2016). "Unexpectedly however, infection-induced PKR phosphorylation required MyD88 but was unaffected by TRIF inhibition compared to the control peptide (CP)." (PMID 27021640, 2016). "Infected larvae with depleted levels of MyD88 showed a higher infection load and a lower survival rate compared to control fish." (PMID 27917158, 2016). "As in the in vivo experiments, the expression patterns of NF-κB, TNF-α and MyD88 in lungs were similar to those of gga-miR-19a throughout the test stages after infection." (PMID 27683641, 2016). "Considering the important role of MyD88 in protection against pathogen infection, we generated a MyD88 RNAi silencing cell line by designing a shRNA expression vector, lentivirus transfection and effective screening." (PMID 27707937, 2016). "Experimental data show exacerbated granulomatous inflammation and necrosis in the lungs of MYD88-/- mice relative to normal controls, a difference that gets more pronounced at 5 weeks after infection." (PMID 28127112, 2016). "In the current study, we uncovered a novel mechanism by which MyD88 enables the development of vaccine-induced anti-fungal Th17 cells and resistance to infection." (PMID 27542117, 2016). "TLR receptor signaling is primarily mediated through the adaptor protein myeloid differentiation primary response gene 88 (MyD88) in response to infection." (PMID 27293547, 2016). "The genes encoding CD14 (42.55 fold) and MyD88 (5.54 fold), two proteins involved in signaling trough TLR4, had increased expression levels during infection." (PMID 27982111, 2016). "IFNγ is linked to moDC development in other models and plasma IFNγ levels were decreased in MyD88-/- compared to WT mice after LCMV-Cl13 infection." (PMID 26808628, 2016). "As expected, LTX-injected MyD88 flies succumbed much more rapidly to ∆HTL infection (LT50 about 24 hours)." (PMID 27767081, 2016). "Now we wished to address how MyD88 mediated signaling affects the infection with W. chondrophila in our zebrafish model." (PMID 27917158, 2016). "The potential role of MyD88 signaling at later time points of an infection needs to be further investigated." (PMID 27917158, 2016). "Since we previously found that WT mice cleared high D39Δcps doses within 24 hours, Myd88-/- and WT mice were sacrificed 6 or 24 hours after infection with D39Δcps, again seeking to obtain information about the early and late host response." (PMID 25700108, 2015). "Inflammation is a crucial response to eliminating an infection and the long form of MyD88 is an essential bottleneck adaptor protein that many TLRs rely upon to propagate signaling pathways." (PMID 26669856, 2015). "After instillation of D39 we euthanized mice 6 or 48 hours after infection for measurements of bacterial loads in lungs and blood, seeking to obtain insight into the role of MyD88 in the early and late host response." (PMID 25700108, 2015).
infection (continued). "At both time points the lungs of MyD88-/- mice contained much higher burdens of D39Δcps as compared to the lungs of WT mice (P<0.005); at 24 hours after infection the average difference was as high as 105-fold." (PMID 25700108, 2015). "Data in MyD88-deficient mice which are highly susceptible to MTB and succumb very rapidly to infection supports a role for MyD88 in regulating MTB infection." (PMID 25312698, 2015). "Surprisingly, when mice were inoculated with LVS 24 hours post-DT treatment, they died rapidly of a neutrophilic pneumonia, well before even MyD88 knock-out mice infected with similar doses of Francisella succumb to infection 28,29." (PMID 26029367, 2015). "BALB/c MyD88-/- mice harbor a striking disruption of their spleen architecture as early as d4 after infection." (PMID 25954804, 2015). "In contrast, the titer of polyreactive antibody in MyD88 null mice at 14 days before infection was only 1,500 and increased to about 3,500 at 7 days after infection." (PMID 26463758, 2015). "This elevation in bacterial load in MyD88- and BomΔ55C flies over the course of infection suggests that Toll signaling in general, and Bom peptides specifically, contribute to resistance." (PMID 25915418, 2015). "We isolated macrophages from wild type and ERK, TLR-2, and MyD88 knock-out mice, infected these cells with H37Rv or H37RvΔTlyA, and investigated bacterial loads at different time points post-infection." (PMID 25847237, 2015). "Specifically, BomΔ55C flies had a median survival of just over two days post-infection, nearly identical to MyD88- flies." (PMID 25915418, 2015). "Strikingly, while WT mice rapidly cleared D39∆cps, Myd88-/- mice showed 105-fold higher bacterial burdens in their lungs and dissemination to blood 24 hours after infection." (PMID 25700108, 2015). "The results showed that MYD88 was significantly upregulated in the H1N1-SS2 group at 2.32-fold compared with that in the other two infection groups." (PMID 25906258, 2015). "To further demonstrate that MJWQH inhibited the NF-κB signaling pathway in the RNA level, we quantified the mRNA levels of TLR7, MyD88, and p65 in lung tissues on day 4 after infection." (PMID 26089947, 2015). "Following infection, more than 50% of MyD88- flies died within one day and nearly all (>90%) were dead within two days." (PMID 25915418, 2015). "Microarray analyses showed a strong induction of genes associated with fibrosis and a downregulation of the red pulp macrophage transcriptomic signature at d6 post-infection in the spleen of BALB/c MyD88-/- animals." (PMID 25954804, 2015). "To compare the impact of MyD88 on host and viral gene expression directly, we measured the expression kinetics of Tnf, Il6 and Ifnb1 with the viral Ie1 gene in the context of the infection of Myd88-/- and WT BMDMs." (PMID 25856589, 2015). "It indicated that TLR4 and MYD88 were significantly increased in H1N1-SS2 infection group, which play important roles in TLR signaling." (PMID 25906258, 2015). "These experiments indicate that MyD88 is necessary for developing full levels of viral enhancer-activation upon infection." (PMID 25856589, 2015). "If Boms contribute to resistance rather than tolerance, the bacterial load in wild-type flies at 44 hours post-infection should be similar to the bacterial load of BomΔ55C and MyD88- flies at 18 hours post-infection." (PMID 25915418, 2015). "We therefore considered it of interest to examine the impact of MyD88 deficiency on the concentrations of proinflammatory cytokines (TNF-α, IL-1β, IL-6) and CXC chemokines (KC, MIP-2) after infection with D39 or D39Δcps." (PMID 25700108, 2015). "Because TLR signalling is involved in the activation and migration of NK cells during infection, we used MyD88−/− and TLR4−/− mice to assess the role of TLR signalling pathways in the recruitment of NK cells in our sterile injury model." (PMID 25609031, 2015).
infection (continued). "Mechanistically, the central TLR-adapter protein MyD88 is shown to play a critical role in promoting viral enhancer activity in the first 6h of infection." (PMID 25856589, 2015). "This differed from in vivo infection data where infected MyD88−/− and DKO mice showed similar levels of elevated serum IL-10." (PMID 26441965, 2015). "In comparison to wild-type mice, the magnitude of γδ T cell expansion at day 3 post-infection was much lower in MyD88−/− and TLR7−/− mice (P<0.05 or P<0.01)." (PMID 25232836, 2014). "Additional experiments showed that SHIP-1 and MyD88 mRNAs were relatively unchanged for the first few hours after infection with LVS, Schu S4, or U112 and then increased between 12 and 18 h, the latest time point examined." (PMID 25295729, 2014). "(TNF-α, 1 h infection; 1.01 ± 0.07, p > 0.05, 6 h infection; 1.27 ± 0.13, p < 0.05, 12 h infection; 1.05 ± 0.05, p > 0.05, 24 h infection; 1.07 ± 0.09 p > 0.05) MyD88 expression increased significantly at 1, 6, and 12 h after M. smegmatis infection." (PMID 25299393, 2014). "Furthermore, the strong association of cytokine ratios with survival in TLR- and MYD88- deficient mice suggests that protection against pathology may be conferred by the ratio of anti-inflammatory to pro-inflammatory cytokines produced during infection." (PMID 25192715, 2014). "(MyD88, 1 h infection; 1.44 ± 0.08, p > 0.05, 6 h infection; 1.47 ± 0.04, p < 0.01, 12 h infection; 2.14 ± 0.12, p < 0.01, 24 h infection; 1.18 ± 0.19, p > 0.05)." (PMID 25299393, 2014). "Taken together, these results demonstrate a role for MyD88 signaling in regulating host innate immune response and in facilitating host survival during concurrent infection with enteric bacterial and helminth pathogens." (PMID 25010669, 2014). "Considered together, the data support a model in which MKP-1 confers early attenuation of proinflammatory cytokine production that is reinforced at later stages of infection by miR-155-dependent downregulation of MyD88." (PMID 25295729, 2014). "The interaction between the M2-2 protein and MyD88 was also investigated in the context of WT and ΔM2-2 infection." (PMID 24618691, 2014). "Specifically, at both days 3 and 6 post-infection, IFNG, IL6, TNF, MIP1B and IL10 were all significantly diminished in MYD88-deficient mice as compared to wild-type mice." (PMID 25192715, 2014). "The infection of macrophages originating from mice defective in the adaptor proteins MyD88 or TRIF revealed that the killing of intracellular Δisp2/isp3 is dependent on both adaptor proteins." (PMID 24732131, 2014). "For this reason, MyD88 is essential for innate defense against invading bacteria and other microbes, and as such contributes to control of primary infection of mice with both LVS and Schu S4." (PMID 25295729, 2014). "Significantly, the results reported in this article have demonstrated a role for MyD88 signaling in host survival during concurrent infection with intestinal parasitic and bacterial pathogens." (PMID 25010669, 2014). "Selective expression of MyD88 in the airway epithelium was sufficient for neutrophil recruitment to the site of infection and bacterial clearance." (PMID 25254554, 2014). "Brucella stimulates both TLR2 and TLR4 and the TLR adaptor MyD88 appears to be essential for controlling infection in vivo." (PMID 24339776, 2013). "In the current study, we tested the role of MyD88, as well as individual receptors and as expected, loss of MyD88 left Sigirr −/− mice suffering severe mucosal damage and rapidly succumbing to infection, much like Myd88 −/− mice that express SIGIRR." (PMID 23950714, 2013). "In summary, we demonstrate that during infection MyD88 signaling is essential for the development of an efficient intracerebral cellular immune response able to control parasite levels." (PMID 23374751, 2013).
infection (continued). "The Yersinia pestis TIR-containing protein YpTdp interacts with MyD88 to reduce IL-1β- and LPS-dependent signaling and to contribute to modulation of cytokine secretion during infection." (PMID 23847770, 2013). "MyD88 signaling plays a key role in the protection against infection with both B. pseudomallei and B. mallei." (PMID 23508691, 2013). "Conversely, there was no significant increase in mRNA expression of CCL5, CCL19, CCL20 and CCL21 chemokines after infection in both MyD88+/+ and MyD88−/− mice." (PMID 23374751, 2013). "Once infection progresses to the chronic phase, it is crucial to determine the implication of MyD88 in the process to limit parasite replication in the brain." (PMID 23374751, 2013). "Once more, MyD88−/− mice revealed symptoms of an infection at the cerebral level with piloelection, huddling, lost of mobility, a tilted head to one side and circling in the cage, indicating a persistence of tachyzoite proliferation in the brain." (PMID 23374751, 2013). "Salmonella enterica serovar Enteritidis TlpA is capable of reducing NF-κB activation by TLR4, IL-1R and MyD88-dependent pathways and to contribute to control of IL-1β secretion during infection." (PMID 23847770, 2013). "In our study, we found that infection of H.pylori activated NF-κB with the overexpression of MyD88, p65/RelA and p50/NF-κB1 in AGS cells." (PMID 23437218, 2013). "To assess if rapid TLR mediated antigen processing contributed to reduced worm burdens, we repeated transfer experiments using B cells isolated from MyD88−/− mice at one day post infection." (PMID 24204255, 2013). "MyD88 signaling thus appears to limit tissue damage during infection by this pathogen, potentially by promoting increased IEC proliferation." (PMID 23950714, 2013). "Using MyD88-deficient C57BL/6 mice infected intraperitoneally with an avirulent strain of T. gondii, they demonstrated that MyD88 was essential for the survival to the acute phase of infection and for early parasite replication control." (PMID 23374751, 2013). "Our results showed that multi-PAMPs can activate CgTLR and Myd88 transcription in oyster hemocyte, suggesting their involvement in pathogen infection of CgTLR signaling." (PMID 24098508, 2013). "Thirteen days after infection, MyD88−/− and MyD88+/+ mice were sacrificed, and their spleens were removed for cellular analysis." (PMID 23374751, 2013). "In MyD88−/− mice, active infection with tachyzoites appears to continue in the brain during the entire period of sulfadiazin treatment." (PMID 23374751, 2013). "We demonstrate the requirement of the MyD88-Traf6 pathway for the infection-triggered induction of miR-146a/b in the zebrafish embryo model." (PMID 24112639, 2013). "MyD88 KO animals displayed significantly increased bacterial burdens on catheters and surrounding tissues during early infection, which coincided with enhanced dissemination to the heart and kidney compared to wild type (WT) mice." (PMID 22879997, 2012). "In contrast, both TLR4−/− and MyD88−/− mice exhibited early delays in systemic spread of infection during the first week, which is accompanied by a delay in clearance at later times." (PMID 22973560, 2012). "Taken together, these results indicate that Heat-VAC infection of pDCs leads to the production of RNA species that are detected by the endosomal RNA sensing pathway mediated by TLR7/MyD88." (PMID 22606294, 2012). "This contrasts with our findings for S. aureus, where titers remained significantly elevated at day 14 post-infection in tissues of MyD88 KO mice." (PMID 22879997, 2012). "Interference with TLR signaling by the organism has been described in numerous studies, as has the prominent contribution of MyD88 in limiting infection." (PMID 22973560, 2012). "The MyD88−/− knockout appears to have a reduced ability to control the infection as evidenced by the significant difference in spleen colonization by week 4 (panel W4)." (PMID 22973560, 2012).